IL4 (interleukin 4)
Diseases named in the same sentence as IL4 in open-access papers (continued):
Sharing a sentence is not in itself a finding about the gene and the disease.
asthma (continued). "In individuals with asthma, exposure to allergens exacerbates this response, leading to heightened airway inflammation and impaired viral clearance due to increased production and secretion of IL-4, IL-5, and IL-13." (PMID 38674586, 2024). "However, severe asthma can remain uncontrolled and requires add-on treatments such as mAbs directly targeting Th2 cytokines IL-4, IL-5 as well as their receptors." (PMID 38566968, 2024). "Also, at high dosages, tiotropium decreased the total number of inflammatory cells, including macrophages and eosinophils, and the levels of transforming growth factor-β1, IL-4, IL-5, and IL-13 in bronchoalveolar lavage fluid in a mouse model of asthma." (PMID 38419021, 2024). "In vitro studies of epithelial and stromal cells frequently simulate T2-high immune environments with addition of the classical Th2 cytokines IL-4, IL-5, and IL-13, but fail to recapitulate many epithelial genes that are differentially expressed in T2-high asthma or nasal polyps in vivo." (PMID 38444858, 2024). "ROC curves indicated that the area under the curve (AUC) of 25-(OH)-D, IL-4, IFN-γ, IFN-γ/IL-4, and joint detection are 0.765, 0.780, 0.853, 0.638, and 0.912 in diagnosis of MP infection-related asthma, and sensitivity and specificity of joint detection are both greater than 95%." (PMID 39572779, 2024). "Asthma generally enhances the IL-4/INF-γ ratio fourfold compared to the sham group." (PMID 39000141, 2024). "In the present study, we estimated whether the IL-4-dependent suppression of neutrophil recruitment contributed to the development of an immune response in asthma." (PMID 39767651, 2024). "IL-4 is a characteristic cytokine of Th2 cells as well as a major cytokine leading to asthma." (PMID 39444792, 2024). "Cytokines like IL-4, IL-5, and IL-13 often propel this immune reaction in asthma." (PMID 39407835, 2024). "For instance, the concentrations of interleukin-4 (IL-4) and IL-6 in the peripheral blood of children with asthma were found to be significantly elevated in comparison to healthy controls, whereas the concentrations of interferon-γ (IFN-γ) were significantly decreased." (PMID 39286809, 2024). "Some pro-inflammatory cytokines relevant to asthma are interleukin (IL)-4, IL-13, IL-17, and IFNγ." (PMID 39197446, 2024). "The joint detection of 25-(OH)-D, IL-4, IFN-γ, and IFN-γ/IL-4 may improve diagnostic capabilities of MP infection-related asthma." (PMID 39572779, 2024). "However, 4-OI reduced M2 gene expression and airway resistance in a murine asthma model, indicating the potential for therapeutic modulation of IL-4-induced pathologies in vivo." (PMID 38487538, 2024). "Subsequently, Hematoxylin and eosin (H&E) staining, Masson’s trichrome (Masson) staining, Periodic acid-Schiff (PAS) staining and inflammatory cytokines assay of interleukin (IL)-4, IL-6, IL-17 were implemented to evaluate the protective effects of Chelidonium majus on asthma." (PMID 38671520, 2024). "Dupilumab is a fully human monoclonal antibody that blocks the shared receptor component for IL-4 and IL-13, inhibiting the signalling of both IL-4 and IL-13, which are key and central drivers of type 2-mediated inflammation in multiple allergic diseases, especially in AD and asthma." (PMID 39340076, 2024). "Similar to our experimental condition, it can be speculated that unique macrophages were induced by LPS and IL-4, in the lung with the asthma with bacterial infection." (PMID 37180123, 2023). "Whilst biologic therapies targeting the type-2 cytokines IL-4, -5, -13 or epithelial alarmins are proving transformative in the management of severe type-2 high asthma, for those with type-2 low inflammation, treatment options remain limited and pathology poorly understood." (PMID 37180449, 2023).
asthma (continued). "Acupoint catgut embedding reduces EOS aggregation and promotes its regulation to alleviate the airway inflammatory response in the episode of asthma, which might be associated with the inhibition of p38MAP, ICAM-1, and IL-4 mRNA expression." (PMID 37740212, 2023). "IL-4, known for its influence on B cell differentiation and antibody production, was upregulated in a manner similar to that observed in inflammatory respiratory conditions like asthma." (PMID 38097754, 2023). "Furthermore, compared to controls, patients with asthma have increased IL-4-producing NK cells in their blood." (PMID 37730635, 2023). "In this study, in comparison to M2 macrophages, LPS/IL-4-induced macrophages showed increased expression of Arg1 whose protein involves in deposition of collagenous and extracellular matrix components in lung parenchyma to make asthma severe." (PMID 37180123, 2023). "It has been shown that miRNA-21 can be successfully used as a non-invasive diagnostic marker of asthma, showing a positive correlation with blood and sputum eosinophilia and IL-4, and a negative correlation with the FEV1 and IL-12 concentration." (PMID 37511254, 2023). "In our study, the amounts of IgE and IL-4 were significantly increased in the OVA-induced asthma model, while both DEX and CE treatments could effectively decrease the levels of IgE and IL-4." (PMID 37765323, 2023). "Therefore, IFN-γ, IL-17, and asthma-related targets IL-4 and IL-10 were considered inflammatory factors for the evaluation of asthma." (PMID 36636604, 2023). "The IL4 and IL13 genes are located in one cluster of chromosome5q31.1 and encode cytokines that play a key role inthe asthma pathogenesis, namely, IL-4 and IL-13 promoteairway eosinophilia, mucus hyperproduction, bronchial hyperreactivity,and IgE synthesis." (PMID 37465198, 2023). "We found that the changes in mRNA expression using publicly available data were evident in some of the predicted target mRNA genes involved in airway inflammation in asthma, FcεRI signaling, IL-4 signaling, and the Th2 pathway, in association with altered IgE expression." (PMID 37076662, 2023). "Microbial differences in asthmatics have an impact on the production of mucins and inflammatory factors, for example, interleukin (IL)-4 and IL-5, and alterations in gut microbial patterns are closely related to the degree of sensitization and inflammation in asthma." (PMID 36636604, 2023). "Thus, type 2 cytokines, such as IL-4, IL-5, and IL-13, are promising therapeutical targets for AR and also other allergic diseases, such as asthma and atopic dermatitis." (PMID 37109185, 2023). "T2 airway inflammation in patients with asthma, although occurring along a continuum, is characterized by a specific set of cytokines, including IL-4, IL-5, IL-13, and the so-called alarmins, IL-25 and IL-33, and thymic stromal lymphopoietin (TSLP), secreted by activated epithelial cells." (PMID 37947596, 2023). "In addition, interleukins, especially IL6 and IL4, were suggested as prospective biomarkers of childhood asthma." (PMID 37241840, 2023). "Furthermore, we were able to investigate relationships between sputum periostin and type 2 cytokines (IL-4 and IL-13) in a smaller, unrelated subset of 30 patients with asthma." (PMID 36763690, 2023). "Type 2 (T2) inflammation is the most common endotype in both asthma and CRSwNP Caucasian populations, and it is characterized by the presence of Th2 and T2 innate lymphoid cells that secrete T2 cytokines (IL-4, IL-5, and IL-13), eosinophilia, and high IgE titers." (PMID 37088840, 2023). "Decreasing the Th2-associated cytokines IL-4, IL-5, and IL-13, and increasing the Th1 cytokine IFN-γ may help to alleviate the inflammatory response in asthma." (PMID 36846048, 2023). "It wasalso determined that the CC genotypes of IL4 rs2243250, IL6rs1800795, IL13 rs1800925 and the allelic variant T of IL12Brs3212220 can be considered to be potentially protective forthe development of uncontrolled asthma." (PMID 37465198, 2023).
asthma (continued). "Anti-IgE therapy markedly reduces both airway inflammation and mast cell activation, as manifested by reduced IL-4 expression, but has a minimal effect on BHR: this suggests that other factors are causally linked to airway hyperresponsiveness to methacholine in asthma." (PMID 37298721, 2023). "The T2 high-associated increase in FeNO levels could be decreased by combined inhibition of IL-4 and IL-13 signalling in 104 patients with persistent, moderate-to-severe asthma." (PMID 40980110, 2023). "Besides, the initial IL-4 levels in the asthma with AURVIs group were greatly upregulated compared with the asthma alone group (305.01 ± 105.59 ng/ml versus 238.13 ± 88.45 ng/ml, p = 0.023)." (PMID 37865742, 2023). "Earlier findings have also shown that cigarette smoke could exacerbate ovalbumin‐induced asthma and markedly enhance the expression of IL‐4 and IL‐13 genes." (PMID 36789047, 2023). "There is also an association between the expression level of OX40/OX40L and severity of asthma, since elevated expression was observed in bronchial submucosa of mild asthma, which was related to the accumulation of eosinophils and the level of IL-4 expression in the lamina propria." (PMID 36865540, 2023). "Furthermore, IL-4 and IL-13 activate the M2 macrophage subtype in patients with either asthma and/or CRSwNP." (PMID 37240477, 2023). "Alongside this evidence of Dupilumab's effectiveness in the treatment of severe asthma, only limited data exist about switching from a previous monoclonal antibody therapy to an anti-IL-4/13 biologic, and all the available information comes from real-life studies." (PMID 37298514, 2023). "Dupilumab, an IL-4/IL-13 receptor blocking antibody, is used in dermatitis as well as asthma." (PMID 37881430, 2023). "IL-4 is a major cytokine in the development of inflammation in asthma." (PMID 37063828, 2023). "In addition, biologics targeting IL-4/1L-13 (dupilumab) and IL-13 (i.e., lebrikizumab) have been shown to suppress serum periostin levels in asthma patients." (PMID 37108417, 2023). "Furthermore, previous research in asthma patients proved exogenous supplementary choline as an anti-inflammatory factor inducing lowered levels of pro-inflammatory cytokines, including IL-4, IL-5, and TNF-α, which are also involved in T1D." (PMID 40303249, 2023). "Furthermore, expression of genes whose expression correlates with asthma, including Il9, Il4, Il13, Ccl11, Ccl24, and Muc5ac, was much lower in recipients of Id1 cKO Th9 cells." (PMID 37867222, 2023). "IL-4 is a potent inducer of the Th2 immune response and is involved in allergy and asthma." (PMID 37296643, 2023). "In asthma, T helper type 2 (Th2) cells, basophils, or mast cells were a source of IL‐4 and IL‐5." (PMID 37773696, 2023). "In asthma, IL-4 plays a main role in regulating type 2 cell expansion and type 2-related cytokine production, as well as, IgE synthesis, while IL-13 has a major role in inducing the clinical features of the disease such as mucus production and airway hyperresponsiveness." (PMID 37753208, 2023). "Type 2 inflammation occurs in approximately 70% of severe asthma patients and is promoted by a broad network of hyper-expressed cytokines, namely IL-4, IL-5, IL-13, and several immune cells, including mastocytes, type-2 helper lymphocytes, type-2 innate lymphoid cells, basophils, and eosinophils." (PMID 37298514, 2023). "A mouse asthma model was given oral/pulmonary administration of AG nanoformulation, and the bioavailability of the drug was greatly enhanced, as was the release of inflammatory factors (such as IL-4, IL-5 and IL-13), which were also significantly reduced." (PMID 35455087, 2022). "TH2-high asthma is characterized by allergic sensitization and eosinophilic inflammation of the respiratory tract, guided by type 2 prototypical cytokines comprising IL-4, IL-5 and IL-13." (PMID 35743783, 2022).
asthma (continued). "Through transcriptional analysis, it was found that the asthma group had upregulated IL-4, IL-5, and IL-10 expression in lung tissue than the normal group, while MS treatment augmented IL-10 and attenuated the elevation of IL-4 and IL-5." (PMID 35812246, 2022). "Additionally, stimulation of HBECs with cytokines associated with asthma (TNF-α, IL-17A, and IL-4) resulted in increased miR-146a." (PMID 36203653, 2022). "Biologic drugs, such as anti-IgE and anti-IL-5, anti-IL-4/IL-13 monoclonal antibodies, are currently being used with clinical success in patients with type-2 diseases, such as asthma and CRSwNP, and only recently some authors suggested their efficacy also in the treatment of comorbid EOM." (PMID 35207196, 2022). "While its role in promoting insulin resistance and type II diabetes has been explored and its function as a regulator of M2 macrophage polarization has been described, not much is known about its precise contribution to the pathophysiology of asthma/allergy through the IL-4 pathway." (PMID 36077511, 2022). "Therefore, the levels of IL-4 and IL-13 were investigated in the blood of healthy children and children with asthma using ELISA." (PMID 36313877, 2022). "It was observed that, in this study, higher IgE concentration, eosinophil count, IL-4, and IL-17A levels were revealed in the asthma exacerbation children than in the remaining children; what is more, these levels increased with the severity of asthma." (PMID 35356750, 2022). "Furthermore, the release of IL-4, IL-5, and IL-13 play a central role in the initiation and development of chronic airway inflammation of asthma." (PMID 36213326, 2022). "Allergies and acute asthma exacerbations are generally induced by IL4." (PMID 36140412, 2022). "Asthma has long been considered as an allergic Th2-driven inflammatory disease, involving the “canonical” Th2 cytokines [interleukines (IL)-4, IL-5, IL-13], eosinophilic inflammation, and mediators of allergic inflammation (mainly immunoglobulins E and mast cells)." (PMID 35386663, 2022). "In this paper, we investigated the expression levels of CLCA1, IL-4, and IL-13 in pediatric asthma." (PMID 36313877, 2022). "However, as our animals have been exposed to radon inhalation therapy, it is also of note that IL-5, alongside with IL-4, is also known to be involved in airway inflammation and hyperreactivity especially in asthma." (PMID 35203348, 2022). "Therefore, when exploring the treatment strategies for asthma of targeted inhibition of pro-inflammatory factors such as IL-4, it is necessary to take the potential unwanted effect of impaired Treg cell function into consideration." (PMID 35898499, 2022). "Asthma and associated type 2 inflammation are driven by both the innate (type 2 innate lymphoid cells) and adaptive [T helper type 2 (Th2) cells] immune systems, characterized by the release of cytokines such as interleukin (IL)-4, IL-5, and IL-13, key pathophysiologic characteristics of asthma." (PMID 35371026, 2022). "Indeed, both the cytokines IL-4 and IL-5 as well as IL-13 were augmented in asthma mice, while the level of anti-inflammatory cytokines IL-2, IFN-ɣ, and IL-10 were drastically reduced." (PMID 36685604, 2022). "In conclusion, Danlong Dingchuan Decoction may act on IL-4, IL-6, IL-8, and other Th2 cytokines and reduce the expression of Th2 cytokines with a variety of active compounds in treating asthma." (PMID 35186104, 2022). "Furthermore, the proportion of IL-17A+ memory Th17 cells is increased in female patients with severe asthma than in male patients, while the proportion of IL-4+ memory T cells is similar in female and male patients with severe asthma." (PMID 35625578, 2022). "We stimulated BEAS-2B cells with IL-4, IL-13 and IL-17A to simulate the asthma microenvironment." (PMID 36575422, 2022).
asthma (continued). "Although historically thought to be derived from conventional Th17 cells, it is now understood that IL-17 is mainly produced by IL-17-producing Th2 cells that co-express ROR-γt and GATA-3 with the capacity to simultaneously produce both IL-4 and IL-17 during the chronic stage of asthma." (PMID 36032162, 2022). "IL-4– and IL-13–driven epithelial cell expression of 15 lipoxygenase 1 (15LO1) is a consistent feature of eosinophil-dominated asthma known as type 2–high (T2-high) asthma." (PMID 34981786, 2022). "Immunomodulators such as anti-immunoglobulin E (IgE), anti-IL5, and anti-IL4 Ra antibodies have shown potential benefits in improving asthma control and reducing acute exacerbation in patients with severe asthma; however, each molecular-targeted medicine is limited to a specific genotype." (PMID 36345503, 2022). "GLA could regulate the Th1/Th2 balance; increase the IL-12 level; decrease the IL-4, IL-5, and IL-13 levels; and inhibit the inflammatory responses in asthma." (PMID 35859797, 2022). "Toxocara infection modulates the immune response to Th2 and the secretion of IL4, IL5, and IL13, which could theoretically be associated with asthma." (PMID 36250067, 2022). "The IL-4/IL-13/STAT-6 pathway is a well-known key regulator in asthma pathophysiology." (PMID 35743888, 2022). "In T2 asthma, the Th2 cytokines IL-4, IL-5, IL-9, IL-13, and IL-25, and the acute proinflammatory cytokines TNF-α, IL-1β, IL-6, and IL-8, subsequently lead to bronchial hyperresponsiveness (BHR), and plasma cells and antibody-producing cells secrete antibodies." (PMID 36430662, 2022). "Interleukin-4 (IL-4) is one of the most important pro-inflammatory mediators in asthma." (PMID 36263132, 2022). "T helper cells type 2 (Th2), another subset of T lymphocytes, is essential in the process of asthma, secreting CKs such as IL-4, IL-5, and IL-13 that directly impair lung tissue or indirectly facilitate the proliferation of IgE-generating B cells and EOS, contributing to AHR and airway remodeling." (PMID 35812246, 2022). "The levels of IL-4 and IL-17 in the recurrent infection group were significantly higher than those in the asthma group, while the levels of IL-21 were significantly lower than those in the asthma group." (PMID 35991273, 2022). "Type 2 innate lymphoid cells (ILC2), type 2 T-helper (Th2) cells, and related cytokines (such as IL-4, IL-5, and IL-13) are major players in the pathological changes and clinical symptoms of asthma, and increasing attention has been paid to anti-IL-5, anti-IL-5Rα, and anti-IL-4Rα therapy." (PMID 36530558, 2022). "In addition, the IL-4 and IL-10 levels in the asthma group were higher than that in the pneumonia group, while the IL-12 and IFN-γ levels decreased." (PMID 36045657, 2022). "IL-4 is an important driver in the initiation of lung inflammation in asthma, including Th2 cell proliferation and IgE synthesis, and high-dose OmeGo significantly reduced IL-4 by 17% (p < 0.05); however, the numeric reduction in serum IgE did not quite achieve significance." (PMID 36289834, 2022). "According to the prediction results of network pharmacology, IL-6, TNF, CXCL8, IL-10, IL-1β, and IL-4 may be the key targets of Danlong Dingchuan Decoction against asthma." (PMID 35186104, 2022). "Besides TH2 cells, also T follicular helper (TFH) cells, a specialized subset of CXCR5+ CD4+ T cells, are a major source of IL-4 and IL-21, thus closely regulating IgE isotype switching during asthma in both humans and mice." (PMID 34342773, 2022). "ELISA measurement of IL-4 and IL-17 from BECs supernatant showed a higher concentration of IL-17 in severe asthma, much higher with severe asthma+E2 group, and the addition of DHT (severe asthma+ DHT) lowered the IL-17 concentration in severe asthma with statistical significance." (PMID 36062195, 2022). "The expression of IL-4 was still significantly elevated in the HDM-induced asthma model." (PMID 36177049, 2022).